MTOR (mechanistic target of rapamycin kinase)
Diseases named in the same sentence as MTOR in open-access papers (continued):
Sharing a sentence is not in itself a finding about the gene and the disease.
cancer (continued). "The mTOR pathway is often upregulated in cancers and promotes generation of these critical metabolic intermediates via modulating the expression or activity of metabolic enzymes or transcription factors." (PMID 31817676, 2019). "Co-inhibition of the PI3K/AKT and RAF/MEK/ERK pathways appears to be constrained for the inhibition of downstream mTOR effector pathways in KRAS mutant cancer." (PMID 31652660, 2019). "Because of similar metabolisms in active Th cells and cancer cells, described in detail above, it is expected that the polyphenols can suppress mTOR activity in Th cells." (PMID 30766532, 2019). "The transcription factor Snail directly represses 4E-BP1 transcription and compromises the anti-cancer effects of mTOR inhibitors." (PMID 31277692, 2019). "The PI3K/Akt/mTOR pathway is critical for autophagy induction and is a latent target in cancer therapeutics and control." (PMID 31781485, 2019). "The induced autophagy by the nanoparticles is responsible for their anticancer effects and AMPK/mTOR pathway plays a vital role in Zn-CuO NPs induced cancer cell autophagy." (PMID 31001120, 2019). "There are many excellent reviews that discuss in detail the role of the PI3K/Akt pathway and mTOR in cancers and neurodevelopmental disorders." (PMID 31413155, 2019). "We investigated its underlying anti-tumor mechanism for the first time and found that RC induced apoptotic and autophagic cell death and inhibited the Akt/mTOR/P70S6K signaling pathway in cancer cells." (PMID 31817918, 2019). "Itraconazole treatment also appears to inhibit the growth of cancer cells by blocking the activation of AKT/mTOR signaling." (PMID 31850214, 2019). "As a critical amino acid transporter, SLC7A5 was mainly involved in regulating proliferation, apoptosis, and chemoresistance of cancer cells through activating the downstream AKT/mTOR pathway." (PMID 31803607, 2019). "Extreme activation of phosphorylation of PI3K/AKT/mTOR signaling is one of the supreme common alterations in human cancers." (PMID 31030467, 2019). "And if so, would it offer increased efficacy in combination with targeting HER2, AKT/mTOR, and/or mitochondrial apoptosis pathways in this cancer subset, or in other FGFR4-overexpressing cancers?" (PMID 30903103, 2019). "The phosphatidylinositol 3-kinase (PI3K)/mammalian target of rapamycin (mammalian target of rapamycin (mTOR)) pathway has been the focus of interest in identifying potential prognostic markers of cancer." (PMID 30863440, 2019). "Studies have found that CD164 overexpression promotes cancer cell migration by activating the CXCR4/PI3K/AKT/mTOR axis." (PMID 31007847, 2019). "c-Fos and mTOR are well-known key players in carcinogenesis, and the effect of its inhibition has been shown by many previous reports to critically control cancer development." (PMID 31167465, 2019). "Because of metabolic similarity between cancer cells and activated Th cells and lack of sufficient data about flavonoids effects on Th cells or the PI3K/Akt/mTOR axis, here we will focus on results from the cancer field." (PMID 30766532, 2019). "The cytotoxic effect of EIF4Ai is noteworthy, as the effect of MTOR inhibitors on cancer cells is cytostatic." (PMID 30072418, 2019). "Mechanistic target of rapamycin (mTOR) is a master growth regulator and its inhibition is one of the best options to treat several cancer types." (PMID 35582567, 2019). "In this case, we chose drugs that block PI3K/MTOR pathway because of the prominent role of the pathway in cancer biology and the abundance of compounds within the GDSC database that target this pathway." (PMID 31685861, 2019).
cancer (continued). "The PI3K/AKT pathway acts as a positive regulator of the mTOR pathway, which serves as a negative regulator of autophagy in cancer cells, so that disruption of the PI3K/AKT/mTOR/p70S6K pathway by anticancer agents induces autophagy." (PMID 30845773, 2019). "The phosphatidylinositol 3-kinase (PI3K)-AKT-mammalian target of rapamycin (mTOR) signaling, as a key oncogenic pathway in various cancers, is clearly emerging as another important mechanism to promote CRPC." (PMID 31092266, 2019). "Cancer growth and development are frequently associated with upregulation of intracellular signalling pathways, including the PI3K/Akt/mTOR pathway, which drives cellular proliferation resulting in the uncontrolled cell growth that defines cancer." (PMID 30056610, 2019). "Our observations are in agreement with a recent review highlighting the importance of the PI3K/AKT/MTOR axis and mitochondrial abnormalities as potential modulators of ASD and cancer associations." (PMID 31007884, 2019). "There are no real treatments for the MCC, even though the first-generation inhibitors of mTOR including rapamycin and other rapalogs are currently being investigated in different cancer types including some skin malignancies." (PMID 31370278, 2019). "Everolimus, an inhibitor of mTOR, has emerged as a potential combination therapy drug for cancer treatment, although everolimus alone only exerts modest anti-cancer effects." (PMID 31480338, 2019). "The central role of the PI3K/Akt/mTOR pathway in the oncogenic process has led to the development of cancer treatments targeting this pathway." (PMID 31227862, 2019). "Deregulation of Aurora kinase A (Aur-A), a member of the mitotic serine/threonine Aurora kinase family, and overactivation of the mTOR pathway commonly occur in multiple cancer types." (PMID 31406104, 2019). "RAS acts as an activator for both MAPK and P13k/AKT/mTOR pathways, emphasizing its important role as a regulator for all the involved pathways and the consequences of its alterations in the case of cancer." (PMID 31652660, 2019). "Autophagy regulation is strictly interconnected with the aberrant setting of cancer cell metabolism as revealed by the fact that mTOR and AMPK pathways are both the master regulators of autophagy and the most critical sensors of the cellular energy status." (PMID 30483817, 2019). "In another preclinical study, a mammalian target of rapamycin (mTOR) inhibitor in combination with a sonic hedgehog inhibitor led to better disease control and chemosensitized the cancer stem cells to cytotoxic agents." (PMID 30645701, 2019). "The mTOR-mediated autophagy in cancer cells seems to be impacted both by AMPK-dependent cytotoxicity and cytoprotection." (PMID 30870998, 2019). "The aim of this study is to investigate the role of PI3K/Akt/mTOR signaling pathway and its association with epithelial-mesenchymal transition (EMT) and cancer stem cell (CSC) marker expression in EOC chemoresistance." (PMID 31234823, 2019). "Observations in murine embryonic fibroblasts and cancer cells showing that modulation of mTOR signaling affected miRNA profiles by altering Drosha activity have previously implied a connection between mTOR and miRNAs." (PMID 30636722, 2019). "The significant increase in transcriptional activity elicited by lactate in both PIK3CA and AKT1 implicates lactate as a signaling oncometabolite of the key PIK3/AKT/mTOR pathway involved in the development of many cancers." (PMID 32010625, 2019). "Subsequently, we sought to explore the effect of PC1 on mTOR signalling in our cancer cell lines when PC1 protein expression is knocked down by siRNA." (PMID 31251475, 2019). "Akt and its downstream effectors, including NF-κB, CREB, and mTOR, function in diverse cellular processes, including cancer progression and insulin metabolism." (PMID 31409352, 2019). "The effects of mTOR inhibition on specific T-cell subsets can be exploited to improve cancer treatment and immunotherapy." (PMID 31817676, 2019).
cancer (continued). "Targeting glutamine uptake and glutaminolysis in cancer patients has the potential to suppress mTOR signaling, even in the presence of aberrant growth factor stimulation." (PMID 30634602, 2019). "Clinical use of rapamycin and other mTOR inhibitors as a cancer and immunotherapy treatment is becoming popular, and there is mounting evidence of the mTOR pathway's importance in neurologic and psychiatric disease." (PMID 31704693, 2019). "In this context, mTOR activity is found deregulated in many types of cancer including breast, prostate, lung, melanoma, bladder, brain, and renal carcinomas." (PMID 31357505, 2019). "The phosphatidylinositol-4,5-bisphosphate 3-kinase (PI3K)–protein kinase B (AKT)–mammalian target of rapamycin (mTOR) signalling pathway, which is inappropriately activated in many cancers, plays a central role in the genesis and progression of NET." (PMID 31527867, 2019). "Previous studies suggested that the activated PI3K/AKT/mTOR signaling pathway can promote cell survival and cancer cell growth by attenuating apoptosis-related signaling, and this effect can result in radiotherapy resistance." (PMID 31430901, 2019). "GJA1, which encodes Cx43, has been shown to synthesize several truncated protein forms through a process of internal translation initiation regulated by key cancer signalling pathways such as mTOR and Mnk1/2." (PMID 30845770, 2019). "Given that the Akt-mTOR signaling pathway is upregulated in platinum-resistant cancer cells, studies demonstrate that mTORC1/2 inhibitor, such as PP242 and MLN0128, can re-sensitize platinum-resistant ovarian cancer cells to carboplatin in vitro and in vivo." (PMID 31277692, 2019). "mTOR is one of the mediators in TGF-β signaling pathways that enhances cancer stemness and drug resistance." (PMID 31277692, 2019). "The mammalian target of rapamycin (mTOR) pathway is abnormally activated in various cancers and thus plays significant roles in cancer cell survival and growth." (PMID 30891950, 2019). "PI3K/AKT/mTOR inhibitors not only impact directly upon cancer cells but can also affect immune cell effector function and to modulate the tumor microenvironment." (PMID 31547471, 2019). "Our results in the current study not only enrich the anticancer potentiality of strophanthidin but also give novel insights into the mechanism of the cytotoxic effect on PI3K/AKT/mTOR signaling for improved cancer treatment." (PMID 32010609, 2019). "It is widely expressed in the central nervous system and has been shown to activate the mTOR signalling pathway, an important network for cancer progression." (PMID 31267007, 2019). "For instance, in the variety of cancer phosphatase and tensin homologue deleted in chromosome 10(PTEN) is mutationally inactivated, leads to an increase in mTOR activity." (PMID 31030499, 2019). "In fact, the mTOR pathway has emerged as a major effector of cell growth and proliferation and is an attractive target for cancer therapy." (PMID 30669284, 2019). "On the other hand, the high ATP production from β-oxidation suppressed AMPK activity, which in turn, liberated the inhibition of mTOR activity and promoted cancer cell growth." (PMID 31372520, 2019). "Here the effect of dual treatment of cancer cells with a pan-Akt and a pan-mTOR inhibitor was explored." (PMID 30056610, 2019). "Quercetin promotes loss of cell viability, apoptosis and autophagy in cancer by reducing β-catenin and HIF-1α stabilization, inducing caspase-3 activation and inhibiting of Akt, mTOR, and ERK phosphorylation." (PMID 31261749, 2019). "In cancer cells, activation of Akt/mTOR signaling pathway resulting in heightening the metabolic rate and cancer cell proliferation is observed." (PMID 31205871, 2019). "mTOR activity is frequently de-regulated in a variety of human cancers, such as breast, prostate, lung, liver, and renal carcinomas." (PMID 31277692, 2019).
cancer (continued). "mTOR complex is recently depicted as a nutrient sensor in metabolism of cancer, especially on glucose and amino acid, nucleotide, fatty acid and lipid, growth factors and other stresses." (PMID 30754640, 2019). "A major development has taken place in the last few years to understand the role of mTOR in cancer development and progression." (PMID 31075885, 2019). "Flavonoids also have anti-proliferative effects on cancer cells through suppression of the PI3k/Akt/mTOR pathway in these cells." (PMID 30766532, 2019). "Next we sought to test the effects of combined PI3Kα and mTOR inhibition on stem-like cancer cells grown in 3-D." (PMID 31492956, 2019). "The approval was based on the RECORD-1 trial (detailed in “The promise of mTOR inhibitors in cancer” section)." (PMID 35582282, 2019). "The PI3K/AKT/mTOR pathway is a very attractive therapeutic target in clinical trials of cancer treatment, and activation of PI3K/AKT/mTOR is closely associated with cell proliferation, survival, and metastasis." (PMID 31762993, 2019). "As the mTOR pathway plays a critical role in cell survival and proliferation, various cancers have been reported to have elevated mTOR activity." (PMID 31167465, 2019). "Most cancer-relevant natural products interact with molecules involved in key intracellular signalling pathways like PI3K/AKT/mTOR/GSK3β, Ras/Raf/MEK/MAPK/ERK1/2, PL-Cγ/PKC/CaMKII/IV or JNK just to mention the classical signalling cascades." (PMID 30609679, 2019). "In this review, we discuss the functions of mTOR in cancer metabolism that have been illuminated from pre-clinical studies." (PMID 31817676, 2019). "Metformin‐mediated AMPK activation is known to inhibit the mTOR signalling pathway, which controls many biological processes including cell proliferation and cell survival in diverse cancer cell lines." (PMID 30710424, 2019). "In colorectal cancer, the knockdown of HSF1 inhibited mTOR activation and glutamine metabolism while attenuating the cancer cell growth in vitro." (PMID 31878360, 2019). "Genomic analysis detected mutations in the PI3K/mTOR pathway in these latter two patients, highlighting that mTOR is a druggable pathway in this cancer." (PMID 31569540, 2019). "Deregulated mTOR signaling was found in ageing and human diseases such as cancer and metabolic diseases." (PMID 30642006, 2019). "In response to mTOR inhibition, however, cyclin D1 is elevated by everolimus in various types of cancer." (PMID 31388935, 2019). "WNT interacts with mTOR signaling to affect cancer cell growth and tumor metabolism, as well as the formation of spermatozoa." (PMID 31890219, 2019). "Several studies have revealed that CEP induces autophagy and apoptosis in various types of cancer cells through the AMPK/mTOR or Akt/mTOR signaling pathways." (PMID 31699152, 2019). "The mTOR controls metabolism and growth of the cells, and thus, is a suitable drug target in variety of cancer types." (PMID 31247018, 2019). "There is a marked interest in targeting mTOR protein kinase, for cancer therapy, also based on genetic studies showing selective effects on tumour cells following mTOR inactivation." (PMID 30795552, 2019). "A number of signaling components both upstream and downstream of mTOR are frequently deregulated or altered in human cancer." (PMID 30764584, 2019). "This increased activity is achieved through signalling by mTOR and sterol regulatory element-binding proteins (SREBPs), which stimulate proliferation in cancer cells through Akt signalling." (PMID 31443386, 2019). "The uptake of glutamine through ASCT2, followed by its rapid efflux through LAT1 in exchange for essential amino acids (EAA) such as leucine is the rate-limiting step for mTOR activation in cancer cells." (PMID 30634602, 2019). "LAT1 enables transport of the EAAs to improve cancer cell growth via mTOR-induced translations, and ASCT2 sustains the cytoplasmic amino acid pool to drive LAT1 function." (PMID 30871192, 2019).
cancer (continued). "PI3K/AKT/mTOR signaling pathway linking to several other pathways and networks regulates cancer proliferation and progression." (PMID 30682771, 2019). "In breast MCF-7 cancer cells, mTOR activates mitochondrial biogenesis by increasing TFAM, mitochondrial ribosomal proteins, and some components of respiratory complex I (NDUFAF2, NDUFAF4, and NDUFS6) and ATPS (ATP5D, ATP5L, ATP5G1, ATP5O)." (PMID 31600993, 2019). "Together, our study suggests that PC1 modulates cell proliferation and migration and interacts with mTOR and Jak signalling pathways in different cancer cell lines." (PMID 31251475, 2019). "Previous reports showed stimulatory effects of mTOR inhibition on the expansion of Tregs, an effect that can be considered detrimental in terms of cancer control." (PMID 30652208, 2019). "Aberrant activation of the phosphoinositide 3-kinase/Akt/mammalian target of rapamycin (PI3K/Akt/mTOR, PAM) signaling is regarded as a crucial hallmark in a broad spectrum of human cancers." (PMID 31069214, 2019). "A prominent role for AKT/mTOR in FGFR signaling has been previously demonstrated in cancer in a number of studies." (PMID 30972293, 2019). "AKT pathway was more often activated (elevated pAKT expression) in luminal A cancers whereas mTOR pathway was more often activated (elevated p-mTOR and pS6, an mTOR downstream target), in luminal B subtypes." (PMID 30729154, 2019). "mTORC1-mediated phosphorylation of 4E-BP1 has been recognized as a critical control point for many cancers, leading to the application of mTOR inhibitors in cancer chemotherapies." (PMID 31201269, 2019). "PPRC1 is an activator of mitochondrial biogenesis, a process regulated by mTOR, highlighting the use of mTOR inhibitors in cancers with aberrant mitochondrial activity." (PMID 30803482, 2019). "The MAPKs and mTOR signaling pathways have been reported to play crucial roles in EGF-mediated cancer development." (PMID 31167465, 2019). "Studies have reported that many cancer cells abnormally activate AKT and PI3K, leading to the activation of mTOR, which activates protein synthesis by phosphorylating downstream p70S6K and 4EBP1 to regulate cancer cell proliferation." (PMID 31835352, 2019). "A lower expression of active forms of mTOR and protein-kinasi 1 p70-S6 (acting as mTOR target) was detected in carcinomas of either large or small cell types, whereas mTOR pathway results frequently activated in pulmonary carcinoids." (PMID 31273555, 2019). "Due to the importance of the mechanistic target of rapamycin (mTOR) pathway in tumor development and progression, mTOR inhibitors have been designed or are under development for cancer treatment." (PMID 30200497, 2018). "CamKII was described to modulate several cellular processes such as carcinogenesis by controlling cancer cell survival including mTOR activation." (PMID 30338034, 2018). "The failure of current treatment modalities in advanced stages of this cancer and drawbacks of already available mTOR inhibitors demand for novel drug candidates." (PMID 29434241, 2018). "Second-generation mTOR inhibitors have been developed, primarily as anti-cancer agents to target the hyperactive mTOR observed in many cancers." (PMID 30096787, 2018). "mTOR is centrally involved in building up cellular bio-mass, which is rate-limiting for hyper-proliferative cancer cells." (PMID 29301334, 2018). "Due to these anti-proliferative properties, cancer researchers have had much interest in the drug target of rapamycin, mTOR." (PMID 29301334, 2018). "The decreased cancer cell proliferation, due to mTOR reduction, has been confirmed in vivo: mice injected with mir-184-transfected MDA-MB-231 cells showed a delayed primary tumor formation and reduced metastatic burden." (PMID 30363988, 2018).